ALDH1A1 (aldehyde dehydrogenase 1 family member A1)
Diseases named in the same sentence as ALDH1A1 in open-access papers (continued):
Sharing a sentence is not in itself a finding about the gene and the disease.
cancer (continued). "ALDH1A1-induced upregulation of SOD2 and GPX4, as well as ALDH1A1 itself, mitigates erlotinib-induced oxidative and carbonyl stress in cancer cells and imparts erlotinib resistance." (PMID 31695757, 2019). "In accordance with the results of cancer cell analysis, this experiment revealed diminished expression of AKR1C1 (FC=1.6-2.4) and ALDH1A1 mRNAs (FC=1.7), as well as upregulation of ALDH1A3 mRNA in xenograft tumors (FC=1.7-4.0)." (PMID 31413744, 2019). "According to a univariate analysis, higher N and cancer stages, extrathyroidal involvement, and CD15, CD44, CD166, and ALDH1A1 positivity were related to a shorter PFS." (PMID 31428052, 2019). "In this regard, the analyses of treated rat carcinoma cells showed a CD44 and ALDH1A1 expression decrease and Bax expression increase." (PMID 30970626, 2019). "Increased ALDH activity has not only been proposed as CSC marker in different tumor types and cell lines but also as therapeutic cancer target, in particular the two ALDH isoforms ALDH1A1 and ALDH1A335–37." (PMID 29416006, 2018). "High ALDH activity is attributed to the increased expression of ALDH1A1 in many types of cancer cells; therefore, ALDH1A1 isozyme is used as a marker for the enrichment of CSC subpopulations from tumors and cancer cell lines." (PMID 30166520, 2018). "Among ALDH1 gene family, isoforms ALDH1A1 and ALDH1A3 are also known as CSCs markers in several cancers." (PMID 28966724, 2017). "Our results suggest that the inhibition of both ALDH1A1 and ALDH3A1, and particularly their reducing-agent-dependent NAD+ reduction activity, should be viewed as targets for the development of anti-cancer therapies." (PMID 28978015, 2017). "Accordingly, we next looked at a potential relationship between 14q32 miRNAs expression and cancer stem cell markers, and we examined the expression of CD44, ABCG2, ALDH1A1, NANOG and c-MYC genes in 53 tumor samples." (PMID 27980227, 2017). "Experiments with murine and human cells indicate that ALDH1 activity, predominantly attributed to isotype ALDH1A1, is tissue- and cancer-specific." (PMID 26783961, 2016). "The subfamily of aldehyde dehydrogenases 1 (ALDH1) isoenzymes, which comprises ALDH1A1, ALDH1A2, and ALDH1A3, is involved in the synthesis of retinoic acid, and has been identified as functional stem cell markers in diverse cancers." (PMID 27724856, 2016). "In this study, we confirm that the high invasive EOC cells forming the spheroids express a high level of a cancer stem cell (CSC) marker, aldehyde dehydrogenase 1 family member A1 (ALDH1A1), which was significantly down-regulated by curcumin treatment." (PMID 27863439, 2016). "ALDH1 has three main isotypes, ALDH1A1, ALDH1A2, and ALDH1A3, and is a marker of normal tissue stem cells (SC) and cancer stem cells (CSC), where it is involved in self-renewal, differentiation and self-protection." (PMID 26783961, 2016). "On the other hand, aldehyde dehydrogenase 1A1 (ALDH1A1), one of 19 ALDH isoforms, affects the ALDH activity of cancer stem cells (CSCs)." (PMID 27152521, 2016). "It shares 62% protein identity with ALDH1A1, an ALDH that has garnered much attention recently as a biomarker of cancer stem cells." (PMID 25950950, 2015). "RT-PCR analysis further revealed that cancer cells upregulate several CSC markers upon co-culture with ADSCs, including SOX2, NANOG, ALDH1A1, and ABCG2." (PMID 25797257, 2015). "All-trans-retinoic acid treatment results in a 50–60% reduction in ALDH activity and proteins of both isozymes, ALDH1A1 and ALDH3A1, leading to the increased sensitization of ALDH1+ cancer cells to chemotherapy." (PMID 25574188, 2015). "Particularly, an inverse relationship between ALDH1A1 expression and BRCA1 is noteworthy in the context of studying cancer stem-like cells and chemoresistance." (PMID 25216266, 2014).
cancer (continued). "To further evaluate the genes responsible for chemoresistance and cell cycle regulation based on the status of ALDH1A1, we have used RT2 Profiler PCR Array for the human Cancer Drug Resistance & Cell Cycle (Ambion)." (PMID 25216266, 2014). "Specifically, ALDH1A1 and ALDH3A1 have been used as markers to isolate normal and cancer stem cells and have a potential functional role in normal and cancer stem cells." (PMID 24405526, 2013). "Multiple studies have demonstrated that invasion and metastasis are mediated by a cellular component that displays high ALDH1 activity, suggesting that ALDH1A1 can be a significant target for cancer therapy." (PMID 23095512, 2012). "Both the expression levels and activity of aldehyde dehydrogenase 1A1 (ALDH1A1) are important features of tumor-initiating and/or cancer stem cell properties in multiple types of human cancer." (PMID 22710732, 2012). "Among them, galectin-3-binding protein and ALDH1A1 were found preferentially elevated in TNBC, whereas CK19, transferrin, transketolase, and thymosin β4 and β10 were elevated in HER2-positive cancers." (PMID 22110952, 2011). "Unlike ALDH3A2, aldehyde dehydrogenase 1 family member A1 (ALDH1A1), 1 family member B1 (ALDH1B1), and 3 family member A1 (ALDH3A1) expression levels are elevated in other malignant tumors and associated with poorer survival outcomes." (PMID 40923024, 2025). "In addition to cancer cell progression, they also investigated the stemness of cancer cells by measuring pluripotent transcription factors (OCT4, Nanog, SOX2, ALDH1A1)." (PMID 40126346, 2025). "Moreover, in osimertinib-resistant cancer cells, S100A9 was found to activate the RA signaling pathway by upregulating ALDH1A1 expression, thereby promoting brain metastasis." (PMID 40708788, 2025). "Further investigation of ALDH1A1, MAOA, and particularly KLF4 in a patient cohort is warranted, and their involvement in maintaining cancer stem cell populations could lead to novel areas of investigation for non-surgical treatment of EEC and LNG resistance." (PMID 38635728, 2024). "Likewise, ALDH1A1, a newer CSC marker, responsible for the oxidation of intracellular aldehydes, has been investigated in several other cancers with variable prognostic findings." (PMID 38371078, 2024). "In general, these findings deviate from the prevailing evidence linking ALDH1A1 overexpression to aggressive tumor behavior and poor prognosis, a connection often justified by the ability of ALDH‐positive cancer cells to form colonies with high tumorigenic potential." (PMID 38400679, 2024). "However, the role of specific ALDH isoforms, such as ALDH1A1, ALDH1A3, ALDH2, and ALDH3A1, as CSC markers has shifted attention towards developing targeted inhibitors to prevent cancer progression." (PMID 38612911, 2024). "The role of ALDH1A1, observed as part of the DRAC-identified multi-protein complex target, in facilitating development of drug resistance in cancer, as described in the literature, may be of relevance when answering this question." (PMID 39689856, 2024). "As theorized by previous authors, it is likely that the ubiquitous enzyme ALDH1A1 does not serve the same role in CSC activity in all cancer types." (PMID 38371078, 2024). "By inhibiting ALDH1A1 and ALDH3A1, it may be possible to overcome resistance to chemotherapy and enhance the efficacy of existing cancer treatments, providing new avenues for combating resistant cancer types." (PMID 39534872, 2024). "Interestingly, the expression of ALDH1A1 and PON1 was significantly higher in NAT than in TN (P < 0.01), suggesting a higher proportion of cancer cells with stem cell properties in the residual tumors following NAT compared with TN tumors." (PMID 36400567, 2023). "Additionally, in cancer cell signaling, β-catenin, a WNT pathway intermediary, plays an important role in ALDH1A1 expression regulation." (PMID 37796037, 2023). "ALDH1A1, a member of the ALDH family, is highly expressed by stem cells in cancer." (PMID 37063972, 2023).
cancer (continued). "In cancer, RA binds to RARα and alternative transcriptional partners are recruited into the nucleus and enhance cell proliferation, drug resistance, and inhibition of apoptosis by activating c-MYC, cyclin D1, and ALDH1A1." (PMID 37686694, 2023). "However, aldehyde dehydrogenase 1A family subunits, including ALDH1A1 and ALDH1A3, are highly considered cancer stem cell markers, and their role in maintaining cancer stemness has been explained previously." (PMID 37645246, 2023). "Since we found that ALDH1A1 and PPP activity influence erythronate levels, increased erythronate could potentially reflect the overexpression of ALDH1A1 or PPP enzymes, which have been described in other cancers as reflecting poor clinical outcomes." (PMID 37893215, 2023). "In the hypercholesterolemic urinary bladder cancer (UBC) mouse model, ezetimibe significantly suppress HFHC-induced serum lipid (TC, LDL-C, and ox-LDL), and decrease the percentage of cancer cells (CK5+, CK14+, and p-STAT3+) and cancer stemness markers (ALDH1A1, CD44, KLF4, and Nanog)." (PMID 35924044, 2022). "Indeed, ALDH1A1 controls cell cycle checkpoints by regulating KLF4 and p21 proteins, which contribute to apoptosis inhibition in cancer stem cells." (PMID 36551502, 2022). "ALDH1A1, a member of ALD1H1 family is a prognostic predictor of many cancers, including CRC." (PMID 35992866, 2022). "Although several reviews on ALDH1A1 are available, no review has been published that discusses the roles of ALDH1A1 in all cancers." (PMID 35814382, 2022). "In addition, immunoblotting assays of cancer stem cell markers, including CD133, OCT4, and ALDH1A1, showed a decrease as KMT2D was knocked down." (PMID 35477537, 2022). "Among the three HCC lines, Huh7 had a high ALDH1A1 expression whereas the other two did not (p<0.001), suggestive of a high cancer stemness of Huh7 cells." (PMID 35860596, 2022). "The data on the expression of stem cell markers CD44, CD24, and ALDH1A1 in the breast tissue of cancer-free women is very limited and no previous studies have explored the agreement between pathologist and computational assessments of these markers." (PMID 36590957, 2022). "Interestingly, SIRT1 gene silencing upregulated the expression of the EMT-related protein E-cadherin and cancer stemness markers kruppel-like factor 4 (KLF4) and aldehyde dehydrogenase 1 family member A1 (ALDH1A1)." (PMID 36291902, 2022). "ALDH1 has three main isotypes, ALDH1A1, ALDH1A2, and ALDH1A3, which are involved in self-renewal, differentiation, and self-protection, and are markers of normal tissue stem cells (SCs) and cancer stem cells (CSCs)." (PMID 35411309, 2022). "Notably, ALDH1A1 and ALDH1A3 are CSCs markers in many tumors and overexpressed in resistant cancer cells." (PMID 35299840, 2022). "ALDH1A1 maintains self‐renewal of CrT/TICs and facilitates the expression and secretion of EGF from CrT/TICs, which subsequently promotes the activation of EGFR signalling in differentiated cancer cells and tumour growth of LUSC." (PMID 36504325, 2022). "Based on a deep understanding of ALDH1A1 in cancer biology, such an opportunity should not be lost while we search for confirmatory patient data to definitively inform clinical practice." (PMID 35855453, 2022). "The Cr(VI)‐induced ALDH1A1 maintains self‐renewal of the CrT/TIC subpopulation and promotes expression and secretion of EGF from CrT/TICs to activate EGFR signalling of differentiated cancer cells, promoting LUSC tumourigenesis." (PMID 36504325, 2022). "On the other hand, cases with positive ALDH1A1 expression achieved a higher pCR rate in comparison to negative ALDH1A1 carcinomas (60% vs. 37.1%; p = 0.048)." (PMID 36139578, 2022). "Positive ALDH1A1 carcinomas presented a higher prevalence of HTILs compared to negative ALDH1A1 cases (57.5% vs. 25.7%; p = 0.005)." (PMID 36139578, 2022). "Based on our findings, we posit that ALDH1A1 activity, rather than the levels should be considered for cancer prognosis." (PMID 33495566, 2021).
cancer (continued). "Moreover, cancer stem cell (CSC) markers CD44 and ALDH1A1 were significantly higher in high-grade TB tumors." (PMID 35083162, 2021). "Several recent studies have shown that ALDH1A1, ALDH2 and ALDH3A1 may be related to different cancers, such as head and neck cancer (HNC), esophageal cancer, cholangiocarcinoma, and colorectal cancer (CRC)." (PMID 34680942, 2021). "In conclusion, we validate a pathway for cancer stemness regulation involving ALDH1A1 levels through the CSN6–TRIM21 axis, which may be utilised as CRC molecular markers and be targeted for therapeutic intervention in cancers." (PMID 32225170, 2020). "Thus, we concluded that the ALDH1A1 and SLUG axis regulated by AXL is involved in tumourigenicity and stemness, and that cancer prevention with EGCG mediates inhibition of the AXL/ALDH/SLUG axis." (PMID 32051483, 2020). "In summary, we performed mechanistic studies illustrating the role of CSN6-facilitated TRIM21 ubiquitination in enhancing ALDH1A1 expression via the OCT1 transcription factor, lending support to the means by which CSN6 activity can lead to the initiation of cancer stemness." (PMID 32225170, 2020). "More importantly, from a clinical perspective, ALDH1A1 overexpression does not significantly correlate with a poor clinical outcome in different cancers." (PMID 32423137, 2020). "Cancer cells were stained with cytokeratin 19 (CK19), CD44, and ALDH1A1." (PMID 32155897, 2020). "For DCIS tissues, compared with both DCIS cancer-adjacent and normal tissues, we detected four up-regulated (GAPDH, HSPA9, CCT4, and SCPEP1) and 48 down-regulated proteins (including KRT10, APOA1, ALDH1A1, and others) in DCIS tissues." (PMID 33194682, 2020). "Furthermore, identification of protein markers such as ALDH1A1, Sox2, CD44, Oct4, CD133, CD24, and Nanog, etc. have been vital in studying CSCs in cancer research." (PMID 31530793, 2019). "We previously made a similar observation for PAC- and TOP-resistant cell lines, where although only a small population of cells was ALDH1A1-positive, all cells showed multidrug drug-resistant protein expression (P-gp—P-glycoprotein, and BCRP—breast-cancer-resistant protein)." (PMID 31412536, 2019). "We further determined the effect of ALDH1A1 activity inhibition on the non-CSC-to-CSC conversion in the 2008 cancer cell line by treating cells with a potent and selective ALDH1A1 inhibitor NCT-50139." (PMID 29752431, 2018). "ALDH1A1 also reciprocates and prevents AURKA degradation, thereby triggering a positive feedback activation loop which drives highly aggressive phenotypes in cancer." (PMID 28193222, 2017). "Therefore, ALDH activity and ALDH1A1 expression have been exploited for the identification and purification of CSC across many different cancer types." (PMID 28320418, 2017). "Treatment of A2780_CR5 cells with PNA3 decreased (25%) ALDH1A1 activity, suggesting HOTAIR inhibition with PNA could reduce the cancer stem cell population." (PMID 28420874, 2017). "High ALDH1 activity and ALDH1A1 overexpression are associated with poor cancer prognosis, though high ALDH1 and ALDH1A1 levels do not always correlate with highly malignant phenotypes and poor clinical outcome." (PMID 26783961, 2016). "ALDH1 and specifically its isotype ALDH1A1 can be useful as a CSC therapeutic target in cancer tissue types that normally do not express high levels of ALDH1A1, such as breast, lung, esophagus, colon, and stomach epithelium." (PMID 26783961, 2016). "Understanding of molecular markers of cancer stem cells in NPC can improve the development of clinical strategies, as seen in inhibition of tumor growth by interference with CD44v6 signaling and a specific ALDH1A1 inhibitor for cancer stem cell target therapy." (PMID 27647953, 2016). "Surprisingly, it has been documented that high ALDH1A1 expression does not always correlate with highly malignant phenotypes and poor clinical outcome in a range of cancers." (PMID 26783961, 2016).
cancer (continued). "ALDH1A isozymes, mainly ALDH1A1 and ALDH1A3, have been also described as markers of cancer stem cells in different tumors and key determinants for the survival and drug resistance of cancer cells." (PMID 25969992, 2015). "Considering that the presence of cancer stem cells is generally associated with poor histopathological grade and worse survival, our results suggested that ALDH1A1 would not deserve to be called a cancer stem cell marker in HCC." (PMID 26160842, 2015). "Of interest, but in conflict with previous reports, the ALDH1A1-overexpressing cells showed no co-expression with any of these cancer stem cell markers." (PMID 26160842, 2015). "ALDH1A1-overexpressing cells appear to function as a differentiation marker rather than as a cancer stem cell marker in HCC." (PMID 26160842, 2015). "On the other hand, stem cell markers such as OCT4, SOX2, NANOG and GATA4 and cancer stem cell (CSC)–like markers including ALDH1A1, CD44 and CD133 were not upregulated." (PMID 25875914, 2015). "Notably, among the 19 ALDH isoforms, ALDH1A1, ALDH1A3, and ALDH3A1 are tied to cancer stem cells." (PMID 39394200, 2024). "Similarly, ALDH1A1 and TWIST1 are highly upregulated in cancer stem cells." (PMID 39334449, 2024). "In cancer, when RA binds to RARα, alternative transcriptional partners, as estrogen receptor α (ERα), are recruited into the nucleus, thus promoting cell proliferation, drug resistance, and inhibition of apoptosis through the activation of c-MYC, cyclin D1 and ALDH1A1 itself." (PMID 35299840, 2022). "Interestingly, SNAI1-KO cells presented higher stem cell frequency and underwent a switch in the expression of cancer stemness signaling genes, with significant upregulation of epithelial KIT, ALDH1A1 and SOX2, and analogous downregulation of mesenchymal CD44 and SOX9." (PMID 36171192, 2022). "Additionally, positive ALDH1A1 carcinomas showed B CD20+ cell infiltration with a higher frequency than tumors with negative ALDH1A1 staining." (PMID 36139578, 2022). "Therefore, bL-mediated downregulation of CD44, ALDH1A1, and DLGAP5 could be an essential mechanism of inhibiting cancer cell proliferation, even though the suppression mechanism by bL is different." (PMID 30513573, 2018). "IHC staining of CD44v6 and ALDH1A1 was observed in cancer tissues, but that of CD24 was not." (PMID 30340457, 2018). "To examine whether activation of Aldh1a1 is critical for TAZ-induced tumorigenesis and cancer stem cell phenotypes, we first treated E10-TAZ-S89A-T cells with increasing concentrations of A37, an Aldh1a1-specific inhibitor recently developed and used by others." (PMID 28415606, 2017). "Among the ALDH1 family subtypes, ALDH1A1 protects tumor cells against various cytotoxic drugs, whereas ALDH1A3 may play an important role in progression and metastasis; both are candidate biomarkers of prognosis in many cancer types." (PMID 28253891, 2017). "Moreover, ALDH1 expression was significantly higher in diffuse-type lymph node metastasis than in the primary tumor, and ALDH1A1 was found to be overexpressed in highly invasive tumors, especially in T3 and T4 carcinomas." (PMID 26783961, 2016). "In conclusion, ALDH1A1-overexpressing cells could appear to be differentiated cells rather than cancer stem cells in HCC." (PMID 26160842, 2015). "As a result, our study showed a negative finding that ALDH1A1 is not a cancer stem cell marker in HCC, but which could propose as an important data for the development of HCC therapy." (PMID 26160842, 2015). "ALDH1A1 expression was significantly higher in malignant tumors than in non-malignant ones." (PMID 24485040, 2014). "In addition, there were 40 ALDH1A1- samples among the primary cancer tissues, and 39 negative cases among the corresponding lymph node tissues (P < 0.05)." (PMID 24938375, 2014).